EPAS1 (endothelial PAS domain protein 1)
Diseases named in the same sentence as EPAS1 in open-access papers (continued):
Sharing a sentence is not in itself a finding about the gene and the disease.
polycythemia (83 papers, 2010 to 2026). Abnormally high mass or concentration of red blood cells in the blood, either due to an increase in erythropoiesis or a decrease in plasma volume. "In patients presenting with polycythemia/PPGL syndromes due to mutations in EPAS1 or prolyl hydroxylases, 18F-FDOPA PET/CT is superior to 18F-FDG PET/CT and 68Ga-DOTA-SSA PET/CT." (PMID 38206185, 2024). "EPAS1-p.P540L variant was originally identified in a single patient from a family with a reported history of congenital erythrocytosis." (PMID 38244120, 2024). "EGLN1 and EPAS1 play an important role in determining the variability in the response to hypobaric hypoxia at altitude and have been linked to the development of polycythemia and associated abnormalities." (PMID 36835089, 2023). "EPAS 1 NG_016000.1:g.84131C>G or rs7557402 has been reported to be probably benign and associated with familial erythrocytosis by the Illumina Clinical Services Laboratory." (PMID 37568921, 2023). "So far, polycythemia has been recapitulated in transgenic mice with either VHL loss or EPAS1 gain-of-function mutation." (PMID 36040300, 2022). "Somatic mutations, germline mutations, and SNPs in EPAS1 are associated with tumorigenesis and polycythemia, a rare disease connected to certain malignancies." (PMID 35267567, 2022). "We previously identified the syndrome of multiple paragangliomas, somatostatinoma, and polycythemia resulting from postzygotic EPAS1 gain-of-function mutations." (PMID 33497361, 2021). "Mutations in EPAS1, encoding hypoxia-inducible factor-2α (HIF-2α), were previously identified in a syndrome of multiple paragangliomas, somatostatinoma, and polycythemia." (PMID 33497361, 2021). "Expression of EPAS1 was detected in more than ten types of cancer and was also associated with other diseases, including erythrocytosis." (PMID 34828399, 2021). "The adaptive variants of EPAS1 reduced hemoglobin concentrations in Tibetans relative to their lowland counterparts, serving as a crucial protection mechanism for excessive erythrocytosis in Tibetans." (PMID 31993089, 2020). "Mutations in the EPAS1 gene encoding HIF2α are almost always somatic, but still often involve a syndromic presentation including polycythemia (elevated volume of red blood cells in the blood) and somatostatinomas." (PMID 32158431, 2020). "Mosaic gain-of-function EPAS1 mutations have been found to cause a syndrome encompassing multiple paragangliomas/pheochromocytomas, somatostatinoma, and polycythemia, also called Pacak-Zhuang syndrome." (PMID 31185588, 2019). "These mice share polycythemia and biochemistry features of the syndrome, demonstrating gain-of-function mutations of EPAS1 in the ODD domain as the causative gene mutation of the syndrome development." (PMID 31091718, 2019). "This indicates that our model also mirrors human polycythemias with gain-of-function EPAS1 mutations that are inherited in a dominant fashion (heterozygote)." (PMID 31091718, 2019). "Concordantly, it is now known that mutations in EPAS1, which encodes HIF-2α, also cause polycythemia, PPGL, and somatostatinoma." (PMID 30135421, 2018). "Pacak-Zhuang syndrome is caused by mutations in the EPAS1 gene, which encodes for one of the three hypoxia-inducible factor alpha (HIFα) paralogs HIF2α and is associated with defined but varied phenotypic presentations including neuroendocrine tumors and polycythemia." (PMID 38418569, 2024). "Several studies have demonstrated that a mutation in EPAS1 could affect oxygen sensing, polycythemia, and hemoglobin level." (PMID 36292756, 2022). "In addition, the mutation of the EPAS1 gene is said to have also an suppressive effect on Hb elevation, and in this way, this population adapted to hypoxia while avoiding polycythemia." (PMID 33397517, 2021).
polycythemia (continued). "Recently, somatic gain‐of‐function mutations in EPAS1 (HIF2A) have been associated with neuroendocrine tumours in the presence of erythrocytosis and, therefore, it may be advised to screen for these events in individuals with known mutations." (PMID 30426472, 2019). "EPAS1/HIF2 alpha mutations are also linked to polycythemia and somatostinoma." (PMID 31362359, 2019). "Several studies have reported that genetic variation in EPAS1 is related to human polycythemia and high-altitude hypoxia adaptation." (PMID 36292756, 2022). "Generally, erythrocytosis-associated mutations in JAK2 are often associated with low EPO, whereas those in EPAS1 are often associated with increased EPO." (PMID 34946900, 2021). "Mosaic or somatic EPAS1 mutations are associated with a range of phenotypes including pheochromocytoma and/or paraganglioma (PPGL), polycythemia and somatostatinoma." (PMID 33300499, 2021). "Four types of erythrocytosis are known to be caused by mutations in genes encoding key players of oxygen-sensing signaling, namely VHL (ECYT2), EGLN1/PHD2 (ECYT3), EPAS1/HIF2α (ECYT4) and EPO (ECYT5)." (PMID 34440324, 2021). "The genetic variation of EPAS1 (HIF-2α) has been reported by pedigree analysis of human familial polycythemia." (PMID 32069878, 2020). "Irp1−/− mice display polycythemia due to derepression of the Irp1-specific target mRNA hypoxia-inducible factor 2α (Hif-2α; also known as Epas1)." (PMID 24896637, 2014). "Missense mutations in the EPAS1 gene have been shown to cause neuroendocrine tumors with or without polycythemia or polycythemia in isolation." (PMID 38418569, 2024). "To discover genetic variants in unexplained erythrocytosis, we performed whole exome sequencing in 27 patients with JAK2-negative polycythemia after excluding the presence of any mutations in genes previously associated with erythrocytosis (EPOR, VHL, PHD2, EPAS1, HBA, and HBB)." (PMID 37428608, 2023). "Of high translational relevance, the first description of a sustained therapeutic response was recently reported in a patient with polycythemia and multiple inoperable PGL caused by a mosaic germline EPAS1 variant who was treated with belzutifan, a selective small-molecule inhibitor of HIF2α." (PMID 36748842, 2023). "One variant in EPAS1 gene had been already reported in the literature as causing erythrocytosis, while the remaining variants were not yet clinically associated with erythrocytosis." (PMID 34349782, 2021). "We present a long-term survey of pediatric liver recipients, evaluating prevalence, outcome and the main potential causes of erythrocytosis, including a comprehensive mutational analysis of commonly related genes (mutations of HBB and HBA, JAK2, EPOR, VHL, EPAS1 and EGLN1)." (PMID 32546701, 2020). "EPAS1-linked polycythemia in the absence of neuroendocrine tumors is known as erythrocytosis type 4 (ECYT4; Mendelian Inheritance in Man (MIM) #: 611783)." (PMID 30135421, 2018). "The observed significant association of EPAS1 SNPs and TED with hemoglobin levels suggests the functional importance of EPAS1 for high‐altitude adaptation because a relatively low hemoglobin level can prevent onset of polycythemia that impairs tissue blood flow and oxygen delivery." (PMID 28116332, 2017). "This could suggest a connection between EPAS1, EGLN1, and Hb production, especially based on what we know about Tibetan and Andean populations whose genetic variation in both genes has been implicated in protecting individuals from erythrocytosis/polycythemia, resulting from living at high-altitude." (PMID 30631144, 2019).
polycythemia (continued). "This discovery could be significant for certain pathologies where the erythropoietic effect is not desirable, such as secondary congenital erythrocytosis where disease develops due to mutations in genes regulating Epo such as VHL, EGLN1, EPAS1, or EPO." (PMID 35682566, 2022).
glioblastoma (80 papers, 2010 to 2026). The most malignant astrocytic tumor (WHO grade IV). "For instance, EPAS1/HIF2A is a hypoxia responsive transcription factor, the over expression of it in glioblastoma enhances the tumor aggressiveness." (PMID 33803224, 2021). "Although caution should be used in the interpretation of EPAS1 as an endothelial marker since it can also be expressed by glioblastoma cells, lack of staining supports irregularities in the blood vessel structure." (PMID 39724753, 2024).
hepatocellular carcinoma (79 papers, 2010 to 2026). A malignant tumor that arises from hepatocytes. "EPAS1, which was found in the LIHC top 10 TFs of three methods, is linked to CXCL12, which plays an important role in metastasis formation of hepatocellular carcinoma by promoting the migration of tumor cells." (PMID 28347313, 2017). "However, EPAS1 has also been described as tumor suppressive in various other cancer types including neuroblastoma, colon cancer, and hepatocellular carcinoma, and shown to reduce tumor growth and improve patient outcomes when overexpressed." (PMID 33218035, 2020). "In addition, EPAS1 is correlated with tumor invasiveness in hepatocellular carcinoma." (PMID 24098529, 2013).
pulmonary hypertension (68 papers, 2014 to 2026). Increased pressure within the pulmonary circulation due to lung or heart disorder. "A newly identified, most likely gain-of-function, double variant in EPAS1 (HIF-2α) has been shown to be highly associated with this high-altitude pulmonary hypertension." (PMID 37843154, 2024). "EPAS1 was also shown by whole-exome sequencing to be highly significantly associated with HA-related pulmonary hypertension in Angus cattle." (PMID 32718338, 2020). "There was an association of double variants in the oxygen degradation domain (ODDD) of EPAS1 in Angus cattle with High-altitude pulmonary hypertension (HAPH)." (PMID 28222154, 2017). "Further evidence supporting the critical role of HIF2α in the development of hypoxic pulmonary hypertension was provided by demonstration of high association of two EPAS1 variants, which are likely a gain-of-function mutation, with pulmonary hypertension in cattle residing at high altitude." (PMID 33578749, 2021). "GPR126 is known to be involved in lung function and the selected EPAS1 variant might have a potential protective effect on hypoxia induced erythrocytosis and pulmonary hypertension." (PMID 29026132, 2017). "Also, EPAS1 has been implicated processes such as erythropoiesis, iron homeostasis, pulmonary hypertension and vascular permeability." (PMID 28222154, 2017). "Thus, a protective allele in EPAS1 might not only reduce the red blood cell count as seen in Tibetans but also protect from extensive pulmonary hypertension in the Andean population." (PMID 29026132, 2017). "The present study aims to explore the relationship between EPAS-1 and ghrelin levels with right ventricular function and pulmonary hypertension in patients with SLE." (PMID 40172400, 2025). "American Angus cattle affected with pulmonary hypertension at altitudes of 1,478 to 2,618 m had a higher frequency of the endothelial PAS domain-containing protein 1 gene (EPAS1) encoding a hypoxia-inducible factor 2 alpha (HIF2α) missense variant." (PMID 38680232, 2022). "A protein variant of hypoxia-inducible factor 2 alpha (HIF2α, encoded by the endothelial PAS domain-containing protein 1 gene,EPAS1) was previously reported to be associated with pulmonary hypertension at altitudes exceeding 2,000 m." (PMID 31543958, 2019). "Our second aim was to identify protein variants encoded by the bovine endothelial PAS domain-containing protein 1 gene (EPAS1), a gene associated with pulmonary hypertension in Angus cattle." (PMID 27746904, 2016). "These genes, such as PLA2G12A, RGCC, C9ORF3, GRIN2B, GRID1 and EPAS1, are involved in high-altitude physiology including angiogenesis, pulmonary hypertension, oxygen intake, defense response and erythropoiesis." (PMID 25270331, 2014). "In addition, EPAS1 is important for cancer progression, angiogenesis, pulmonary hypertension, and the progression of chronic obstructive pulmonary disease (COPD)." (PMID 35071338, 2021). "There are many reports in the literature linking the expression of EPAS1 with the development of pulmonary hypertension in the event of alveolar hypoxia, but to our best knowledge, no mechanism has been demonstrated so far in which EPAS1 could contribute to the development of arterial hypertension." (PMID 39456823, 2024). "In mice, PH induced by chronic hypoxia or pulmonary arterial hypertension (PAH) caused by Tie2-mediated Phd2 (Egln1, official gene symbol) disruption can be prevented by global or cell-specific deletion or heterozygous knockout of Hif2α (Epas1, official gene symbol; 3–7)." (PMID 39159362, 2024). "EPAS1, known as hypoxia-inducible factor-2 alpha (HIF-2A), serves as a transcription factor participating in many cellular pathways and has been revealed to regulate the function of SMC in pulmonary hypertension." (PMID 39207146, 2024).
neuroblastoma (67 papers, 2007 to 2026). Neuroblastoma (NB) is the most common solid, extracranial childhood tumor. "In contrast, neuroblastoma cells belonging to more undifferentiated high-risk tumors exhibit lower levels of EPAS1." (PMID 41118218, 2025). "The high expression of EPAS1, also known as hypoxia-inducible factor 2 alpha (HIF2α), is significantly associated with a better overall survival rate in neuroblastoma." (PMID 41189817, 2025). "Westerlund and colleagues showed that EPAS1 expression correlates with features of low-risk neuroblastoma." (PMID 37361539, 2023). "In some cancers, e.g., head and neck, lung, and neuroblastoma, a higher EPAS1 level was associated with a better prognosis." (PMID 36230822, 2022). "For example, EPAS1 expression is associated with a better outcome of patients with neuroblastoma and low-risk tumors." (PMID 33042797, 2020). "The role of HIF2α, encoded by EPAS1, in neuroblastoma remains controversial." (PMID 41118218, 2025). "The clear correlation of EPAS1 with increased patient survival, low-risk tumors, and noradrenergic differentiation prompted us to test whether increased levels of HIF2α in neuroblastoma cells would affect key cellular properties such as proliferation and differentiation." (PMID 41118218, 2025). "To map the expression of EPAS1 in neuroblastoma in situ, we performed RNA-scope with probes for EPAS1, TH, and the endothelial marker ENG (Endoglin) in tumors of different stages." (PMID 41118218, 2025). "Through analysis of several bulk sequenced datasets of neuroblastoma patient samples we have previously shown that high expression levels of EPAS1 are strongly correlated with increased patient survival and features typical of low-risk tumors." (PMID 41118218, 2025). "Our data suggest that EPAS1 knockout cells exhibit enhanced self‐renewal, in line with observations in neuroblastoma cells with aberrant HIF‐2α expression which are more immature, stem cell‐ and neural crest‐like." (PMID 32940375, 2021). "A different role in regulation of neuroblastoma has been suggested for HIF-2α (EPAS1- endothelial PAS domain-containing protein 1)." (PMID 33644043, 2021). "With the novel engineered method, they identified 27 proteins with specific binding to the promoter of EPAS1 in neuroblastoma cells." (PMID 34828399, 2021). "Although no miRNA has been proposed to directly target HIF-2 levels in human endothelium to date, recent work indicates that miR-588 in neuroblastoma stimulates HIF-2α expression through interaction with 5′ UTR of EPAS1 mRNA." (PMID 29383635, 2018). "These analyses, together with our evaluation of Wnt3a/Rspo2 effects on neuroblastoma cell biology, reveal that Wnt regulates recently discovered drivers of differentiation such as EPAS1 and BMP4 in cell lines that undergo differentiation." (PMID 29505958, 2018). "EPAS1/HIF-2α, which was very recently associated with differentiation of neuroblastoma was also upregulated after treatment." (PMID 29505958, 2018). "In addition, analysis of the 498SEQC dataset showed that RGS5, NDUFA4L2, and COX4I2 are all significantly correlated with EPAS1 expression in neuroblastoma." (PMID 41118218, 2025). "To understand whether EPAS1 expression also is correlated with chromaffin markers in neuroblastoma tumors, we analyzed the R2 database, utilizing the 498SEQC dataset." (PMID 41118218, 2025). "This supports our previous analysis of EPAS1 expression within the same lineage during mouse development as well as our analysis of EPAS1 expression within the development of the human lineage and in neuroblastoma." (PMID 41118218, 2025). "For example, in mouse adipocyte cells the involvement of transcription factors SP1 and SP3 in EPAS1 expression has been suggested, while in neuroblastoma cells, phosphatidylinositol 3-kinase (PI3K) and serine/threonine-protein kinase mTORC2 have been demonstrated to regulate its transcription." (PMID 34209205, 2021).
neuroblastoma (continued). "Interestingly, a functional binding site of miR-145 in the 3′-untranslated region (3′-UTR) of EPAS1 mRNA was also confirmed in neuroblastoma cells." (PMID 29383635, 2018). "The expression of EPAS1 is significantly positively correlated with the expression of some genes, including NTRK1, which are involved in neuronal differentiation, in neuroblastoma." (PMID 41189817, 2025). "Although previous studies have mentioned its involvement in brain tumors such as neuroblastoma and GBM, few studies focused on the roles of EPAS1 in GBM invasion." (PMID 31487431, 2019). "There is a similar lack of overlap between PNMT and EPAS1 expression in neuroblastoma as in the developing adrenal medulla, potentially reflecting a N-type like, rather than E-type like, chromaffin identity in cells with elevated EPAS1 levels." (PMID 41118218, 2025). "For example, treatment with EPAS1 inhibitors did not block in vitro neuroblastoma cell proliferation or xenograft growth in the mouse model." (PMID 33042797, 2020). "The results in this study are consistent with an earlier study wherein dual treatment of neuroblastoma cells with the demethylating agent 5-Aza-2’-deoxycytidine and retinoic acid inhibited xenografted tumor growth while inducing EPAS1 expression along with several HIF2α target genes." (PMID 41118218, 2025). "Notably, analysis of sequenced neuroblastoma patient samples, revealed a negative correlation between EPAS1 and MYCN expression and a strong positive correlation between EPAS1 expression, high expression levels of noradrenergic markers, and improved patient outcome." (PMID 41118218, 2025).